CD4 (CD4 molecule)
Diseases named in the same sentence as CD4 in open-access papers (continued):
Sharing a sentence is not in itself a finding about the gene and the disease.
breast cancer (continued). "In addition to retrospectively analyzing the associations with OS and RFS in breast cancer patients, we further determined the prognostic value of intra-tumoral CD4+ and CD8+ T cells for the prediction of risk of breast cancer development during the follow-up period." (PMID 25968569, 2015). "Increasing evidence indicates that regulatory T cells (Tregs), a specialized subset of CD4+ T cells, play a central role in breast cancer initiation, progression, and therapeutic response by shaping an immunosuppressive tumor microenvironment." (PMID 42273688, 2026). "For instance, higher intratumoral CD4+ and stromal CD8+ counts in breast cancer were independently associated with improved survival, suggesting their potential as prognostic biomarkers." (PMID 40475782, 2025). "KEGG and GO pathway analysis detected T-cell-related pathways, while other pathways, such as breast cancer, Wnt signaling, and cellular senescence, are commonly found in both T47D and CD4+ T cell ATAC-seq peak analyses." (PMID 41225146, 2025). "In breast cancer, tsMHC-II activates CD4 + T cells by presenting tumor-specific neoantigens, distinct from tsMHC-I, driving anti-tumor immunity." (PMID 40495188, 2025). "A comparison between control samples and patients with luminal A breast cancer revealed significant phenotypic alterations in CD4+ and CD8+ T cell subsets." (PMID 41301880, 2025). "In breast cancer, high FAM155B expression was associated with increased infiltration of M0 macrophages and decreased presence of resting memory CD4+ T cells and resting dendritic cells." (PMID 40746721, 2025). "Patients with breast cancer exhibited reduced CD3+CD4+ T lymphocyte, CD3+CD8+ CTL, and CD33+CD15− M‐MDSC levels compared with healthy controls." (PMID 39749673, 2025). "To determine if these differential peaks sufficiently distinguish between samples from breast cancer patients and healthy donors, we compiled a peak list containing all differentially enriched regions from both T47D and CD4+ T cells (2804 genomic regions)." (PMID 41225146, 2025). "Research has shown that in breast cancer survivors with persistent fatigue, T lymphocyte levels are elevated, particularly CD4+ T cells." (PMID 40098703, 2025). "For example, Fusobacterium nucleatum, which has been linked to colorectal and breast cancer, interacts with TIGIT and CEACAM1 on the surface of CD4+ T cells, inhibiting their cytotoxic potential." (PMID 40943371, 2025). "The authors concluded that TNF-α and IFN-γ produced by TSLP-stimulated CD4+ T cells play a major role in providing antitumor immunity against experimental breast cancer." (PMID 40873585, 2025). "Similar to what we observed in the mammary tumor model, we found a large reduction in the regulatory CD4+ T cells." (PMID 40361381, 2025). "It has been used in several clinical studies of breast cancer and prostate cancer because it contains li-key that can enhance immune response and have epitope amplification effect, thereby inducing CD4+ T cell response targeting HER-2." (PMID 40342927, 2025). "Our findings reveal that TSLP-stimulated CD4+ Th2 cells suppress mammary tumor growth by promoting IL-24+ TAM development and IL-24–mediated tumor cell apoptosis." (PMID 39782693, 2025). "We demonstrated that the induction of TSLP by topical calcipotriol treatment inhibited mammary tumor growth by activating CD4+ T cells." (PMID 39782693, 2025). "Our FACS analysis of PBMC fractions from breast cancer patients confirmed a higher frequency of CD4+ T cells, although the proportions varied among individuals." (PMID 41225146, 2025). "STAT4 expression was also stimulated with an increase in cytotoxic CD4+ T cell numbers, boosting its anti-breast cancer action." (PMID 41010015, 2025). "Patients with breast cancer exhibited lower CD3+CD4+ T lymphocyte, CD3+CD8+ CTL, and CD33+CD15− M‐MDSC levels compared with healthy controls." (PMID 39749673, 2025).
breast cancer (continued). "Depletion of CD4+ T cells, CD8+ T cells, or both with anti-CD4/CD8 neutralizing antibodies effectively restored RCOR2-KO1 tumors in the murine TUBO mammary tumor model." (PMID 40608411, 2025). "We uncover the efficacy of topical calcipotriol for breast cancer therapy, which relies on inflammatory CD4+ Th2 cell-macrophage crosstalk to induce IL-24-mediated tumor cell death." (PMID 39782693, 2025). "Intriguingly, single-cell data from breast cancer patients undergoing ICB revealed that both CD4+CXCL13+ and CD8+CXCL13+ T cell populations possess predictive value for ICB treatment response." (PMID 40883281, 2025). "We have previously demonstrated that TSLP-stimulated CD4+ Th2 cell immunity suppresses early stages of breast cancer development." (PMID 39782693, 2025). "Regarding IFN-γ down-regulation, our observation is in accordance with the suppression of IFN-γ production by CD4+ cells in E0771 and PyMT breast cancer models." (PMID 39877637, 2025). "For example, high CXCL10 levels were associated with CD4+ and CD8+ T cell infiltration in the TME in breast cancer, but in CRC and NSCLC high CXCL10 levels were associated with shorter survival." (PMID 40589738, 2025). "In the 4T1 mouse mammary tumor model, VACV-encoded mIL2 expression remarkably increased CD4+ and antigen-specific CD8+ T cell populations." (PMID 41050655, 2025). "Consistently, Icosl-KO breast cancer cell lines directly induce ICOS expression in CD4+ and CD8+ T cells." (PMID 40708008, 2025). "We observed a positive correlation between LDHC expression and B cell infiltration in Her2-enriched tumors, macrophages and dendritic cells in luminal B tumors, and CD4 + T cells across all breast cancer samples." (PMID 40108668, 2025). "In breast cancer, eosinophils infiltrating lung metastases can promote CD4+ and CD8+ T cell recruitment." (PMID 40050933, 2025). "Breast cancer patients were found to have significantly higher percentages of monocytes, and lower percentages of pDCs and CD4+ T cells in PBMC." (PMID 40948783, 2025). "An intriguing aspect of this analysis is the pairwise error analysis which reveals the elevated potential for IL-2 versus IL-4 signal misidentification in CD4 + T cells in breast cancer patients." (PMID 41166390, 2025). "In this context, breast cancer cells have CD4+T-cells (CD4+CD73+T cells) that express P-gp and enhance the secretion of inflammatory and anticancer cytokines." (PMID 40352931, 2025). "Specific examples include the Aiduqing formula, which inhibits the expression and secretion of CXCL1 by TAMs, thereby inhibiting the chemotaxis and differentiation of initial CD4+ T cells to Tregs as a means to inhibit breast cancer metastasis." (PMID 40242756, 2025). "Breast cancer lacks a control between normal tissues and adjacent tissues, and its immune microenvironment is dominated by CD4 T cells, CD 8T cells, fibroblasts, epithelial cells, macrophages and B cells." (PMID 39120585, 2024). "Studies have further characterized that TILs consisting of an increased CD8+/CD4+ T cell ratio and of natural killer (NK) cells correlated with patient survival and therapy response in breast cancer, suggesting that cytotoxic immunity favors tumor destruction." (PMID 38968186, 2024). "Studies in breast cancer models revealed that these CD4 + T cells accelerate tumor development through secretion of IL-4 and IL-13." (PMID 38557942, 2024). "CAFs in breast cancer with an immunosuppressive phenotype secrete CXCL12 that in turn recruits CD4+ T cells to the TME and are then polarized to regulatory T cells (Treg) by interacting with CAFs." (PMID 39310770, 2024). "CD19+B cells are thought to promote breast cancer development and metastasis through the secretion of IL-10 and induction of the conversion of CD4+T cells to Treg in the mouse models." (PMID 38263363, 2024). "Increased CD4+ memory T cells have been detected in tumor-draining lymph nodes of breast cancer patients." (PMID 39323626, 2024).
breast cancer (continued). "In summary, cytotoxic CD4+ T cells emerge as a promising prognostic biomarker within the immune microenvironment of breast cancer." (PMID 39507526, 2024). "Clinically, the elevation of CD4+CD25+FOXP3+ Tregs in the peripheral blood has been found to be associated with a higher risk of tumor recurrence and a poor prognosis in breast cancer patients." (PMID 38177106, 2024). "Our observation that TCF1 is also expressed by CD4 + T cells clearly supports that further analysis is needed to better characterize the various states of TILs in breast cancer." (PMID 38349444, 2024). "The results showed that CD8+ T cells, macrophages (M1), CD4 memory resting T cells and resting mast cells were reduced in the brain metastasis of breast cancer." (PMID 39157383, 2024). "Fascinatingly, the results of this study indicate that breast cancer derived shCCT2 exosomes promote the Ca2+ influx in CD4+ T cells, while CCT2 exosomes inhibit Ca2+ influx." (PMID 39079960, 2024). "Usually, the main tumor-infiltrating immune cells isolated from breast cancer are CD4+ and CD8+ T cells, in addition to B cells and tumor-associated macrophages." (PMID 38793599, 2024). "TGF-β secreted by tumor-evoked Bregs (tBregs) induces the conversion of naive CD4+ T cells into FoxP3+ Tregs in a 4T1 mammary tumor model." (PMID 38629061, 2024). "Since tumor culture medium affects CD4+ T cells activation, we explored the exact mediators that are responsible for this effect via fractionation of the components of the breast cancer cell culture media." (PMID 39079960, 2024). "Among these biomarkers, CD3+T cells, CD4+T cells, CD4+/CD8+ ratio, CD3+CD4−CD8−T cells, and LMR were identified as independent risk factors for breast cancer development, and the AUCs were 0.760, 0.750, 0.598, 0.697, and 0.761 (P < 0.05), respectively." (PMID 38263363, 2024). "Reduced CD3+T cells, CD4+T cells, DNT cells, CD4/CD8 ratio, and LMR were considered to be independent risk factors for the development of breast cancer." (PMID 38263363, 2024). "In Maturation stages of T cell group, CD45RA-CD4+%CD4+(P = 0.035, OR = 1.029, 95%CI = 1.002~1.058) and EM CD4+AC (P = 0.021, OR = 1.024, 95%CI = 1.003~1.045) were positively correlated with breast cancer." (PMID 39418291, 2024). "We then exposed CD4+ T cells to culture medium (CM) from CCT2-knockdown or CCT2-overexpressing breast cancer cells to compare their ability to modulate the T-cell response." (PMID 39079960, 2024). "The results showed that the proportions and amounts of CD8+ T cells and CD4+ T cells were higher in primary breast cancer than in breast cancer brain metastasis." (PMID 39157383, 2024). "The results of univariate COX analysis indicated that resting dendritic cells, eosinophils, resting mast cells, monocytes, and memory CD4 T cells resting were protective factors for the prognosis of breast cancer patients (hazard ratio [HR] < 1, P < .05)." (PMID 38181289, 2024). "Only one study investigating specific immune cells reported that BMI changes since age 18 were associated with increased CD4 and CD163 levels in breast cancer." (PMID 39769193, 2024). "This recruitment was marked by concomitant changes in immune cell types such as an increase in neutrophils in breast cancer and increases in monocytes and CD4+ T cells in pancreatic cancer." (PMID 38193115, 2024). "Among breast cancer patients, those who achieved pCR had higher levels of CD4 + T cells, NK cells, and LMR before NAT (P < 0.05)." (PMID 38834662, 2024). "Most interestingly, we discovered that exosomal CCT2 derived from breast cancer cells suppressed the activation and proinflammatory cytokine secretion of CD4+ T cell." (PMID 39079960, 2024). "Immune suppressive CD4+ Treg and Th1 Teff in breast tumors showed the highest expression of IL32β, followed by TA-specific CD4+Teff in the blood of breast cancer patients." (PMID 39211051, 2024).
breast cancer (continued). "The results revealed that breast cancer exos were internalized by CD4+ T cells, with red fluorescent spots observed in the cytoplasm." (PMID 39079960, 2024). "Univariate COX analysis showed that dormant dendritic cells, eosinophils, resting mast cells, monocytes, and resting CD4 memory T cells were the protective factors for the prognosis of breast cancer patients (hazard ratio [HR] < 1, P < .05)." (PMID 38181289, 2024). "Together, these results suggest that CCT2 in breast cancer cells-derived exosomes modulate CD4+ T cells activation through the Ca2+-NFAT1 pathway, ultimately compromising antitumor immunity." (PMID 39079960, 2024). "Several immune microenvironment factors, such as B cells naive, T cells CD4 memory resting, T cells follicular helper, T cells regulatory (Tregs), and Macrophages M0, were significantly different in breast cancer." (PMID 38308230, 2024). "In this study, we found that apCAFs were correlated with CD8+ and CD4+ T cells, indicating that in breast cancer, apCAFs play a positive role in the suppression of tumor growth and metastasis." (PMID 39157383, 2024). "The ratio of CD8+/CD4+ T cells in the tumor microenvironment and the percentage of dendritic cells in peripheral blood increased significantly in breast cancer model mice injected with nano-drugs through the tail vein." (PMID 39697556, 2024). "In the years following diagnosis, breast cancer survivors experienced decreases in circulating percentages of CD4+ helper T cells." (PMID 38358741, 2024). "Breast cancer patients exhibit at least two types of Tregs, differentiated by their site of maturation: naturally occurring CD4+CD25+ Tregs (nTregs) in the thymus and inducible Tregs (iTregs) in peripheral tissues." (PMID 39507526, 2024). "In the present study, we observed these same shifts in breast cancer survivors relative to cancer-free participants, with lower CD4+ helper T-cell levels seen after radiation exposure and higher B-cell levels seen after chemotherapy." (PMID 38358741, 2024). "A study with a mouse 4T1 model of breast cancer demonstrated that the secretion of IL-10 by B lymphocytes acts in a TGF-β-dependent manner to promote the conversion of naive CD4+ T cells to Foxp3+ Tregs." (PMID 38533507, 2024). "Compared with women who remained free of breast cancer, women diagnosed with breast cancer had decreases in the circulating percentage of total CD4+ helper T cells (−1.50% [95% CI, −2.56% to −0.44%]; P = .01)." (PMID 38358741, 2024). "Our investigation revealed the presence of CCT2 in breast cancer cell-derived exosomes, which contributed to the suppression of CD4+ T cells activation and proinflammatory cytokine secretion." (PMID 39079960, 2024). "Further investigations in patients have revealed the expansion of CD4+ CTLs in various tumor types, including breast cancer." (PMID 39507526, 2024). "Here, we demonstrated that breast cancer derived shCCT2 exosomes promoted NFAT1 activation in CD4+ T cells, whereas CCT2 exosomes had the opposite effect." (PMID 39079960, 2024). "For instance, TNFSF10-deficiency in breast tumors has been linked to decreased tumor-infiltrating CD4+ and CD8+ T cells in a mouse model of breast cancer." (PMID 38535990, 2024). "Taken together, the results demonstrate that breast cancer cell exos-derived CCT2 inhibits CD4+ T cells activation by limiting CD40L expression via the Ca2+-NFAT1 signaling pathway." (PMID 39079960, 2024). "This study highlights that CD4+ follicular helper T cells within tertiary lymphoid structure germinal centers can predict survival and response to neoadjuvant chemotherapy in breast cancer." (PMID 39620224, 2024). "It is noteworthy though that, in human breast cancer xenografts grown in humanized mice, blocking the recruitment of naïve CD4+ T cells into PV areas of tumors resulted in reduced numbers of intra-tumoral Tregs, and inhibited tumor progression." (PMID 38090569, 2023).
breast cancer (continued). "hASCs had the potential to activate and induce proliferation of resting allogeneic CD4 T cell fraction of PBMCs, or naïve CD4 T cells, derived from breast cancer patients in direct and/or transwell co-culture." (PMID 37462786, 2023). "This study describes the characteristics of circulating CD4+Th cells in patients with breast cancer and demonstrates for the first time that surgical treatment of breast cancer creates a new balance between immune suppression and immune stress in patients." (PMID 36925914, 2023). "Thereto, in the E0771 breast cancer model, we evaluated the T-cell compartment more in detail and observed a shift towards Tregs within the CD4+ T-cell population." (PMID 37622122, 2023). "In vitro trials in both lung and breast cancers indicated that FGFR-TKI enhances infiltration of CD4+ helper T-cells and CD8+ effector T-cells and inhibits the generation of Treg cells and end-depleted T-cells." (PMID 36966334, 2023). "Among breast cancer patients, 40% exhibited a normal CD4+/CD8+ ratio, 20% had an inverted ratio, and 40% had a high ratio." (PMID 37324393, 2023). "In this study, the proportion and number of circulating CD4+CD57+ T cells in patients with breast cancer increased, and immunosenescence occurred." (PMID 36925914, 2023). "generated single‐cell maps of PT and paired LNmet in eight patients with breast cancer and reported that B and CD4 T cells were enriched in the microenvironment of LNmet; however, CD8 T cells, cancer‐associated fibroblasts and mast cells were abundant in PT." (PMID 38009315, 2023). "In conclusion, this study found significant changes in circulating CD4+Th subsets in patients with breast cancer, which were related to clinicopathology." (PMID 36925914, 2023). "Other studies have already indicated that T cells play an essential role in limiting tumor development and that in breast cancer, CD4+ and CD8+ infiltrating T cells are abundant in high-grade ductal carcinoma in situ as well as in invasive carcinoma." (PMID 37046602, 2023). "In conclusion, combining cryo-thermal therapy with anti-IL-6 treatment induced CD4+ Th1-dominant immunity to achieve long-term survival of breast cancer-bearing mice with an MDSC-dominated immunosuppressive environment." (PMID 37108179, 2023). "Reaching out to another publication, it was shown that CGA exhibits its anti-cancer benefits in breast cancer treatment by increasing the percentage of CD4+ and CD8+ T cells in the spleens of experimental mice." (PMID 38001777, 2023). "Comparing to 30 other cancer types, our analysis reveals that the interaction effects of HRD only manifest in breast cancer, typically promoting the beneficial survival effect of T cell, CD4 T cell, Tregs, and Th cell." (PMID 37283742, 2023). "Breast cancer contains multiple cell types, which includes B, NK, CD4 T conv, CD8 T, Neutrophils, Mast, Endothelial, DC, Fibroblasts, Mono/Macro, and Myofibroblasts." (PMID 36820551, 2023). "Low-risk breast cancers had significantly higher abundance of naïve B cells, plasma cells, CD8 T cells, and resting CD4 memory T cells and lower abundance of M0, M1, and M2 macrophages than high-risk breast cancers." (PMID 36936412, 2023). "As the results showed, “CD8 T cell, am-CD4 T cell, γδ T cell, and M0” were different expressions in breast cancer, amongst which “CD8 T cell, γδ T cells, and M0” were correlated with drug score." (PMID 37388747, 2023). "In this study, we evaluated the characteristics and postoperative dynamic changes in circulating CD4+Th cell subsets in patients with breast cancer." (PMID 36925914, 2023). "Thymic Stromal Lymphopoietin (TSLP)-stimulated CD4+ T cells play a vital role in antitumor immunity in advanced breast cancers." (PMID 36761753, 2023). "In this study, we explored the characteristics and postoperative dynamic changes in circulating CD4+Th subsets in patients with breast cancer." (PMID 36925914, 2023).